RNU6-46P (RNA, U6 small nuclear 46, pseudogene)
Synonyms: RNU6-46
Gene: Small nuclear RNA gene on chromosome 11 (67,895,631 to 67,895,737, forward strand). Ensembl gene ENSG00000206587.
Homologues: Orthologues: pig U6 (95% identical), mouse Gm23690 (86% identical), rat LOC120094406 (80% identical). Paralogues in human: RNU6-1 (95% identical), RNU6-2 (95% identical), RNU6-39P (95% identical), RNU6-3P (95% identical), RNU6-4P (95% identical), RNU6-5P (95% identical), RNU6-6P (95% identical), RNU6-9 (95% identical), RNU6-10P (94% identical), RNU6-12P (94% identical), RNU6-13P (94% identical), RNU6-16P (94% identical), and 1286 more.